CRP (C-reactive protein)
Diseases named in the same sentence as CRP in open-access papers (continued):
Sharing a sentence is not in itself a finding about the gene and the disease.
ischemic stroke (continued). "Third, in accordance with the previous data and earlier work from our groups, we measured higher CRP levels in the sera of patients obtained at admission as compared to healthy controls, and high CRP levels measured on day 3 were strongly associated with an unfavorable outcome of ischemic stroke." (PMID 22206485, 2011). "Inflammatory biomarkers, including interleukins, CRP, and vascular cell adhesion molecule 1, have been demonstrated to have value in the early diagnosis of ischemic stroke and in predicting clinical outcomes." (PMID 41543379, 2026). "To date, among CRP–lymphocyte composite markers, only the lymphocyte-to-CRP ratio (LCR) has been evaluated in ischemic stroke patients undergoing mechanical thrombectomy, in a single-center cohort (n = 196)." (PMID 41300897, 2025). "A 2010 meta-analysis of 54 long-term studies of 160,309 patients without history of vascular disease demonstrated the association of CRP concentrations with the risk of later developing CHD, ischemic stroke and vascular mortality." (PMID 41010838, 2025). "The mean CRP level was higher in ischemic stroke patients (28.90 mg/L) compared to hemorrhagic stroke patients (22.80 mg/L), with a p-value of <0.001." (PMID 39258059, 2024). "It is feasible to predict the severity andearly outcome of an ischemic stroke based on the serum C-reactive protein level at the time of admission; however, this predictivecapability does not extend to hemorrhagic stroke." (PMID 40092874, 2024). "In contrast, hemorrhagic stroke patients exhibit a lower mean CRP level of 22.80 mg/L with an SD of 10.97, and a 95% CI for ischemic stroke patients ranges from 19.75 to 25.85 mg/L." (PMID 39258059, 2024). "Mean serum CRP 1–2 months after the ischemic stroke was 9.77 mg/L with standard deviation of 20.41 mg/L in the moderate cognitive impairment without dementia group and 14.37 ± 23.92 mg/L in the dementia group, compared to 6.56 ± 12.41 mg/L in the normal group." (PMID 41542283, 2024). "Several studies have shown that elevated D-D and hs-CRP are predictors of poor prognosis in ischemic stroke." (PMID 39669377, 2024). "The non-ischemic stroke group had significantly higher C-reactive protein (76.76 ± 88.32 vs. 29.74 ± 51.49; p < 0.001) and significantly lower albumin (3.56 ± 0.72 vs. 3.80 ± 0.73; p = 0.035) levels than did the ischemic stroke group." (PMID 39734631, 2024). "Its association with PSD has sparked significant interest, identifying CRP as a prognostic indicator for acute ischemic stroke outcomes." (PMID 38377025, 2024). "On the other hand, higher CRP levels indicate a pronounced inflammatory response in ischemic stroke, emphasizing inflammation's role in its pathophysiology." (PMID 39258059, 2024). "The current study reports that ischemic stroke patients exhibit significantly higher CRP levels, with a mean of 28.90 mg/L, an SD of 7.48, and a 95% CI ranging from 26.79 to 31.01 mg/L." (PMID 39258059, 2024). "The mean CRP level for patients with ischemic stroke is significantly higher at 28.90 mg/L with an SD of 7.48 and a 95% CI ranging from 26.79 to 31.01 mg/L." (PMID 39258059, 2024). "Even for ischemic stroke, intracerebral hemorrhage, and aneurysmatic subarachnoid hemorrhage, CRP is a popular outcome predictor, which is independently associated with short- and long-term mortality and functional outcome." (PMID 38791046, 2024). "After PSM, among 34,024 patients, cardiac complications or death within 30 days of the index ischemic stroke occurred in 5624 (33.1%) patients with CRP levels > 3 mg/L compared to 3947 (23.2%) in those with CRP levels < 1 mg/L (HR 1.51, 95% CI 1.45–1.58)." (PMID 37119383, 2023). "Fourth, increased inflammatory biomarkers (C-reactive protein and erythrocyte sedimentation rate) have been shown to increase poor outcomes in ischemic stroke." (PMID 37189031, 2023).
ischemic stroke (continued). "CRP levels in ischemic stroke patients in the regenerative-compensatory period are affected by BMI, cortisol levels (stress hormone), and disability score assessed by mRS." (PMID 36769677, 2023). "Valeric acid produced by Oscillibacter was higher in ischemic stroke patients and positively correlated with the level of high sensitivity C-reactive protein (CRP) and white blood cell counts." (PMID 38029089, 2023). "Among patients with available CRP measurement within 24 h after the ischemic stroke, 17,044 (16.2%) patients had CRP levels < 1 mg/L, 21,643 (20.6%) had CRP levels of 1–3 mg/L and 66,054 (63.2%) had CRP levels of > 3 mg/L." (PMID 37119383, 2023). "As reported in the literature, most studies that analyzed the relationship between CRP and ischemic stroke outcomes used mortality or subsequent vascular events as the primary outcome measure." (PMID 36769677, 2023). "They showed higher median level of CRP and lower median platelet count compared to other ischemic stroke." (PMID 37034098, 2023). "CRP levels within the first 24 h of an ischemic stroke predict 30-day cardiac complications or death." (PMID 37119383, 2023). "The primary aim of the study was to analyze changes in serum CRP levels in patients after ischemic stroke during the regenerative-compensatory period and to assess the usefulness of CRP as a potential biomarker during the rehabilitation period." (PMID 36769677, 2023). "To date, there is no universally accepted cut-off point in the literature for the infectious CRP levels in studies on ischemic stroke." (PMID 36769677, 2023). "In particular, after an ischemic stroke, CRP has been found to be an independent predictor of long-term death." (PMID 36766637, 2023). "The primary aim of the study was to analyze factors affecting serum CRP levels in patients after ischemic stroke during the regenerative-compensatory period." (PMID 36769677, 2023). "Published studies have paid little attention to the correlations between Lp-PLA2 activity (or mass) and other ischemic stroke biomarkers, including CRP, MMPs, IL-6, TNF-α, VCAM1, ICAM1, S100B, vWF, BNGF, and MCP1." (PMID 36313479, 2022). "Univariate analysis showed that serum VPN, Hb, Hcy, hs CRP, and SBP were associated with vascular cognitive impairment in patients with ischemic stroke (P < 0.05)." (PMID 35480518, 2022). "While in REGARDS cohort study by Byrd has been demonstrated that individuals in highest LIS quintile compare to healthy individuals resulted to 4.29 times increasing in CRP concentration in ischemic stroke patients." (PMID 35232437, 2022). "The highly sensitive C-reactive protein (hs-CRP) level was higher in the ischemic stroke group than in the non-ischemic stroke one (p = 0.001)." (PMID 35345487, 2022). "The CRP concentration on the first day following ischemic stroke (CRP-1) was in the upper limit of the normal range (4.96 mg/L; N < 5mg/L), while the number of WBC was 7.32 thousand/mm3 and was, therefore, in the normal range (n 9.8 thd/mm3)." (PMID 35330458, 2022). "A potential prognostic biomarker of ischemic stroke is CRP, which is currently used to assess pathological inflammation and the progression of atherosclerosis." (PMID 35659067, 2022). "CRP levels increased after ischemic stroke, and high levels of CRP decreased glomerular filtration rate." (PMID 35720359, 2022). "Hs-CRP levels were higher in the ischemic than in the non-ischemic stroke group (p = 0.001), especially in the MCA (2.66 ± 2.22 mg/L) and PCA groups (2.47 ± 1.92 mg/L)." (PMID 35345487, 2022). "The inflammatory response is also characterised by increased levels of C-reactive protein (CRP), an acute phase reactant used as a sensitive marker of systemic inflammation, strongly associated with the risk of CAD, ischemic stroke, and vascular mortality." (PMID 35956022, 2022). "The average CRP concentration on the first day of ischemic stroke was 4.96 mg/L; on the third day, it was 11.76 mg/L; on the seventh day, it was 17.17 mg/L." (PMID 35330458, 2022).
ischemic stroke (continued). "A full-range CRP test is critical for identifying patients who require intensive treatment or close follow-up after ischemic stroke or MI." (PMID 35817770, 2022). "Additive interaction analysis between hs-CRP and family Enterococcaceae for first-ever ischemic stroke." (PMID 36385753, 2022). "The aim of this 3-year follow-up prospective study was to evaluate suPAR levels in patients with a first ischemic stroke in correlation with CRP, PCT, NT-proCNP and endothelin 1-21 and to investigate the impact of suPAR on the outcome." (PMID 35053782, 2021). "The blood C reactive protein (CRP) levels were elevated in patients during the acute phase of ischemic stroke at three altitudes and were significantly higher in highland areas (p < 0.001)." (PMID 33916503, 2021). "In our study, the CRP levels were elevated in patients with ischemic stroke at three altitudes, and were particularly significant at highland areas, with a more than twice as high CRP level in Huzhu and Yushu." (PMID 33916503, 2021). "An additional potential concern are reports that fecal valeric acid is positively correlated with the pro-inflammatory C-reactive protein in patients with ischemic stroke." (PMID 34444880, 2021). "In ischemic stroke, several studies reported a variation in the time points of CRP measurement for prognosis." (PMID 32220241, 2020). "Various blood-based biomarkers were found to be significantly associated with ischemic stroke from cardioembolic etiology including BNP/NT-proBNP, d-dimer, CRP, TNF-α, IL-6, and IL-1β." (PMID 33050269, 2020). "In the general population, high CRP is an independent predictor of cancer-, cardiovascular-, and overall mortality and ischemic stroke." (PMID 32646381, 2020). "In this context, this study evaluated the gender differences regarding periodontal status, oxidative stress parameters/plasma antioxidant capacity, and C-reactive protein in patients who suffered a recent large artery atherosclerosis ischemic stroke." (PMID 32512870, 2020). "A body of evidence suggests that ischemic stroke results in inflammation, leading to an increase in C‐reactive protein (CRP) and various cytokines serum levels." (PMID 32583980, 2020). "Based on this background, a clinical trial investigating selective CRP apheresis after ischemic stroke was initiated (CASTRO1 trial: “Selective Depletion of C-reactive Protein by Therapeutic Apheresis (CRP-apheresis) in Ischemic Stroke”, ID: NCT0441723)." (PMID 32932587, 2020). "Demographic data, periodontal status, oxidative stress parameters/plasma antioxidant capacity, and C-reactive protein in patients who suffered a recent large artery atherosclerosis ischemic stroke were reccorded." (PMID 32512870, 2020). "The aim of the CASTRO trial is to evaluate if CRP apheresis can be applied safely in patients with ischemic stroke and efficiently lower the CRP level." (PMID 32932587, 2020). "Elevated levels of CRP (3–6 μg/ml) are a known predictor of ischemic stroke and TIA, as shown in a large study based on the Framingham cohort." (PMID 32733466, 2020). "We investigated associations of CRP and fibrinogen with risks of incident major coronary events (MCE), ischemic stroke (IS) and intracerebral hemorrhage (ICH) in a cohort of Chinese adults." (PMID 32221345, 2020). "Jeon showed that clopidogrel resistance in ischemic stroke patients is significantly asssociated with a higher white blood count and C-reactive protein (CRP) level." (PMID 32899176, 2020). "Similar to patients with ischemic strokes, thromboembolism results in an inflammatory reaction with raised leukocyte count and CRP." (PMID 32571345, 2020). "Elevated CRP and SAA1, which we observed in the ischemic stroke subtype comparisons or in CBS deficiency, were also observed in Han Chinese ischemic stroke patients and in cardioembolic and large-vessel childhood arterial ischemic stroke." (PMID 31242583, 2019).
ischemic stroke (continued). "Using the first quartile of CRP as the referent, the mHR for ischemic stroke by second, third, and fourth quartiles were 1.19 (95% CI, 0.92-1.53), 1.05 (95% CI, 0.81-1.37), and 1.60 (95% CI, 1.23-2.08), respectively." (PMID 31127075, 2019). "The studies included in this review found that several serologic markers, including CML, CRP, tHcy, estradiol, DHT and resistin, are associated with an increased risk of ischemic stroke." (PMID 31127075, 2019). "Most studies that have examined the relationship between CRP and ischemic stroke outcome have used mortality or subsequent vascular events as the primary outcome measure." (PMID 30294205, 2018). "Ultimately, age, admission SBP, CRP, fasting glucose, ventricular extension, previous ischemic stroke/TIA, and high-grade WMH were adopted into multivariate modeling." (PMID 29681881, 2018). "Several studies have reported that higher levels of inflammatory markers such as C-reactive protein (CRP), interleukin-8, and interleukin-6 are associated with worse outcome after the ischemic strokes." (PMID 30294205, 2018). "The Women’s Health Initiative (WHI) Observational Study showed that C-reactive protein, another biomarker of systemic inflammation, was an independent predictor of ischemic stroke in post-menopausal women." (PMID 29391065, 2018). "Although several studies have shown the higher level of CRP in patients with ischemic stroke, its potential role in various stroke types, particularly in ischemic and hemorrhagic stroke, needs to be investigated." (PMID 29951057, 2018). "Several inflammatory biomarkers, such as C-reactive protein (CRP), total homocysteine (tHcy), tumor necrosis factor receptor 2 (TNFR2), and VEGF, have been found to be associated with an increased risk of ischemic stroke." (PMID 28928981, 2017). "On the other hand, there are conflicting ideas against considering CRP as prognostic biomarker for ischemic stroke outcome." (PMID 27757207, 2016). "Identification of CRP-associated genetic variants provided an alternative aspect to elucidate contribution of CRP to ischemic stroke." (PMID 27460564, 2016). "Because a large body of literatures are based on the studies conducting the relationship between CRP and ischemic stroke outcome by determination of mortality as an outcome measure." (PMID 27757207, 2016). "Meanwhile, observational studies also found that elevation of plasma C-reactive protein (CRP), an important inflammatory marker, was associated with increased risk of ischemic stroke." (PMID 27460564, 2016). "In the present study, we selected HNF1A as a candidate gene of ischemic stroke and focused on several single nucleotide polymorphisms (SNPs) of HNF1A that were known to be associated with circulating CRP levels." (PMID 27460564, 2016). "Many investigators have demonstrated that a high CRP level after ischemic stroke is a predictive factor of poor outcome." (PMID 27355961, 2016). "But also pro-inflammatory mediators such as C-reactive protein (CRP) and Interleukin-6 (IL-6) are increased in ischemic stroke patients who develop an infection." (PMID 25613713, 2015). "The aim of this study was to evaluate the diagnostic value of the serum biochemical markers high-sensitivity C-reactive protein (hs-CRP), D-dimer (DD) and fibrinogen (Fg) in differentiating etiological subtypes of ischemic stroke." (PMID 25680111, 2015). "Clinical studies have demonstrated that increased level of inflammatory parameters related to acute phase reaction such as interleukin-6 or C-reactive protein (CRP) predicts unfavorable outcome in ischemic stroke patients." (PMID 24531853, 2014). "In another study, 38 % of ischemic stroke patients had normal CRP levels on days 1 and 90, 40 % had elevated CRP on both days, 14 % demonstrated an increase from normal to elevated, and 8 % showed a decrease from elevated to normal values." (PMID 24531853, 2014).
ischemic stroke (continued). "The aim of the present study was to assess the possible role of highly-sensitivity C-reactive protein (hs-CRP) in predicting short-term functional outcome of ischemic stroke." (PMID 24353532, 2013). "Elevations of proinflammatory cytokines and C-reactive protein in plasma after ischemic stroke have been reported in both clinical and experimental studies." (PMID 24349350, 2013). "The acute-phase response, characterized by elevated plasma concentrations of IL-6, C-reactive protein and neutrophil leukocytosis, is induced within hours of ischemic stroke." (PMID 24349350, 2013). "It was also demonstrated that C-reactive protein predicts the prognosis of patients with functional disability after the first occurrence of ischemic stroke and correlates to the infarct volume." (PMID 22206485, 2011). "The finding that C-reactive protein (CRP) antigen levels parallel the course of TAFI both in the acute (increase) and later phase (decrease) of ischemic stroke further support an association between hemostasis and inflammation in this disease." (PMID 20657835, 2010). "The higher level of CRP among the individuals with T2D further established the role of inflammation in the pathogenesis of carotid atherosclerosis as one of the key contributors to ischaemic stroke." (PMID 41296388, 2025). "After ischemic stroke, IL-6 elevation has been shown to correlate with increased CRP levels." (PMID 41300897, 2025). "In ischemic stroke, CRP levels rise within 6–24 h post-onset, often peaking between 48 and 72 h." (PMID 40869247, 2025). "Furthermore, inflammatory markers, such as C-reactive protein (CRP) and interleukin 6 (IL-6), have been associated with the risk of ischemic strokes." (PMID 40231146, 2025). "Elevated HDL levels may protect against ischemic strokes due to their anti-inflammatory properties, while higher CRP levels in ischemic strokes indicate a strong inflammatory response." (PMID 39258059, 2024). "The results of logistic regression model showed that the increase of Lp(a), TG/HDL‐C, HBA1C, Lp‐PLA2, CRP, CysC, Hcy, and NLR could increase the risk of carotid artery unstable plaque in patients with ischemic stroke (p < .05)." (PMID 38376047, 2024). "The results showed that the increase in Lp(a), TG/HDL‐C, HBA1C, Lp‐PLA2, CRP, CysC, Hcy, and NLR could increase the risk of carotid artery unstable plaque in ischemic stroke patients (p < .05)." (PMID 38376047, 2024). "We included 585 ischemic stroke patients with baseline data on CRP levels." (PMID 37848651, 2024). "Elevated CRP levels were observed in ischemic stroke patients with ESS." (PMID 39588332, 2024). "CRP is an acute-phase inflammatory protein that can increase significantly at sites of infection or inflammation, and it is a known predictor for severity and outcome in ischemic stroke." (PMID 39634547, 2024). "After PSM, among 33,138 patients, the primary composite outcome of cardiac complications or death within 30 days of the index ischemic stroke were reported in 4243 (25.6%) patients with CRP levels 1–3 mg/L compared to 3891 (23.5%) among those with CRP levels < 1 mg/L (HR 1.10, 95% CI 1.05–1.15)." (PMID 37119383, 2023). "The question arises whether CRP in the acute phase of ischemic stroke, prior to mechanical thrombectomy (MT), might help predict outcomes." (PMID 37360331, 2023). "In conclusion, despite demonstrating a significant relationship between CRP levels and corresponding mRS scores, CRP levels alone may not serve as an independent predictor of long-term functional outcomes in ischemic stroke patients undergoing rehabilitation." (PMID 36769677, 2023). "In this study, we are interested in finding out whether CRP levels in the acute phase of ischemic stroke can help explain the outcome disparities in patients with endovascularly treated LVO." (PMID 37360331, 2023).